MPC1 (mitochondrial pyruvate carrier 1)
Diseases named in the same sentence as MPC1 in open-access papers (continued):
Sharing a sentence is not in itself a finding about the gene and the disease.
cholangiocarcinoma (8 papers, 2018 to 2024). A carcinoma that arises from the intrahepatic biliary tree (intrahepatic cholangiocarcinoma) or from the junction, or adjacent to the junction, of the right and left hepatic ducts (hilar cholangiocarcinoma). "For example, it was reported that MPC1 upregulation promoted the metastasis of cholangiocarcinoma by reversing Warburg effect." (PMID 38615083, 2024). "PGC-1α also upregulates MPC1 in cholangiocarcinoma and breast cancer, but in these cases ERRα-mediated MPC1 transcription seems to be required for tumor progression." (PMID 33804985, 2021). "MPC1 also plays an important role in enhancing cholangiocarcinoma cell migration and invasion capabilities." (PMID 34059057, 2021). "In contrast to COUP-TFII, peroxisome proliferator-activated receptor-gamma co-activator (PGC)-1 alpha (PGC-1α) was found to increase expression of MPC1 in human renal cell carcinoma and cholangiocarcinoma." (PMID 32708919, 2020). "Besides, downregulation of peroxisome proliferator-activated receptor-gamma co-activator (PGC)-1α was also reported to contribute to MPC1 silencing at transcriptional level in breast cancer, renal cell carcinoma and cholangiocarcinoma." (PMID 38615083, 2024). "Previous studies have shown that MPC1 can transport pyruvate into the mitochondria for oxidation, reducing lactate production in PGC1α-transduced cholangiocarcinoma cells, but elevating reactive oxygen species (ROS) production to facilitate metastatic dissemination of cholangiocarcinoma cells." (PMID 30770798, 2019). "Downregulation of MPC1 or MPC2 has been observed in several types of human cancers such as kidney, cholangiocarcinoma and breast cancer." (PMID 38615083, 2024). "In cholangiocarcinoma, elevated PGC1α increased PDHA1 and mitochondrial pyruvate carrier 1 expression through the transcription program, thereby promoting cancer metastasis." (PMID 37056926, 2023). "In cholangiocarcinoma, PGC1α reverses the Warburg effect by switching Warburg effect-related aerobic glycolysis to OXPHOS and upregulating MPC1 and pyruvate dehydrogenase E1α subunit expression, which facilitate tumour migration and invasion." (PMID 34059057, 2021).
lung carcinoma (7 papers, 2016 to 2025). "Recently, it has been reported that higher MPC1 expression correlates with an increased number of immune cells in human cervical and lung cancers, indicating an enhanced antitumor immune response." (PMID 39920561, 2025). "This suggests the importance of the MPC1/STAT3 axis in the progression of lung cancer and provides a new perspective for molecular targeting of the STAT3 pathway." (PMID 39179991, 2024). "In lung cancer, MPC1 works with mitochondrial signal transducer and activator of transcription 3 (mito-STAT3) to reduce cytoplasmic STAT3." (PMID 34059057, 2021). "Decreased MPC1 expression enhances lung cancer cell invasion and migration abilities via matrix metalloproteinase (MMP) pathways, and MMP2, MMP3, and MMP7 are significantly overexpressed in an MPC1 knockdown mouse model." (PMID 34059057, 2021). "There are studies showing low levels of MPC1 expression in colon, kidney and lung cancers, and the expression of MPC1 correlates with poor prognosis." (PMID 27852261, 2016). "In lung cancer, MPC1 expression is lower in LUAD tissue than in non-tumour tissue and is remarkably associated with favourable prognosis." (PMID 34059057, 2021). "Studies indicate that the interaction between MPC1 and mitochondrial STAT3 (mito-STAT3) disrupts the distribution of STAT3, reduces the activity of cytoplasmic STAT3 (cyto-STAT3), and promotes the malignant progression of lung cancer, including invasion and metastasis." (PMID 39179991, 2024).
renal cell carcinoma (7 papers, 2019 to 2024). "The authors of this study reported that MPC1 and PGC1α expression is downregulated in renal cell carcinoma (RCC)." (PMID 34199142, 2021). "In human renal cell carcinoma, decreased MPC1 expression might lead to impaired mitochondrial respiratory capacity in renal cell carcinoma cells through the upstream gene regulation of PGC1α." (PMID 34059057, 2021). "Low MPC1 levels correlate with a poor prognosis in several cancers, including renal cell carcinoma." (PMID 33920080, 2021). "Finally, MPC1 was found to be downregulated in renal cell carcinoma tissue when compared with adjacent non-cancerous tissue, and lower MPC1 expression correlated with unfavorable prognosis for renal cell carcinoma patients." (PMID 32708919, 2020). "In kidney cancer, protein and mRNA levels for MPC1 and MPC2 are lower in advanced renal cell carcinoma (RCC) tumors compared to normal adjacent tissue, and decreased MPC1 expression in RCC correlates with worse survival outcomes." (PMID 32784379, 2020). "In renal cell carcinoma, PGC-1α regulates MPC1 transcription by recruiting ERRα to the ERRα response element 2 on the MPC1 promoter." (PMID 32784379, 2020).
breast cancer (5 papers, 2017 to 2024). A primary or metastatic malignant neoplasm involving the breast. "It have been confirmed that MPC-1 is secreted steadily and continuously in mouse mammary tumor, and over expression of MPC-1 can directly inhibit T cells to secret IFN-γ." (PMID 28207826, 2017). "Additionally, Prox1 represses PDK1 and induces MPC1 in breast cancer cells." (PMID 37508533, 2023). "It was also shown that decreased expression of MPC1, interfered with pyruvate entry into mitochondria and increased cellular reliance on glutamine oxidation and the pentose phosphate pathway to maintain reduced NAD phosphate (NADPH) homeostasis in breast cancer." (PMID 34445210, 2021).
glioblastoma (5 papers, 2020 to 2023). The most malignant astrocytic tumor (WHO grade IV). "Increased MPC1 expression via COUP-TFII inhibition slows growth of human glioblastoma cell lines and decreases tumor volume in xenograft studies with immune-deficient mice." (PMID 32784379, 2020). "In brain cancer, patient data from The Cancer Genome Atlas (TCGA) show that low MPC1 expression in glioblastoma correlates with worse patient survival and resistance to chemotherapy." (PMID 32784379, 2020). "Deletion of MPC1 is related to a poor prognosis in glioblastoma." (PMID 35968507, 2022). "Certainly, MPC-deficient cells are more resistant to radio- and chemotherapy in vitro, and it was reported that patients treated with temozolomide for glioblastoma showed poorer survival when their tumors expressed low levels of MPC1 compared to patients with MPC1-intact tumors." (PMID 33804985, 2021). "In glioblastoma, data from The Cancer Genome Atlas and the Genotype Tissue Expression database revealed a negative correlation between Mpc1 expression and overall survival and response to temozolomide." (PMID 33804985, 2021).
lung adenocarcinoma (5 papers, 2019 to 2021). A carcinoma that arises from the lung and is characterized by the presence of malignant glandular epithelial cells. "In lung adenocarcinoma, MPC1 deficiency accelerates lung adenocarcinoma progression through the STAT3 pathway." (PMID 32851100, 2020). "Lastly, in lung cancer, low MPC1 expression in lung adenocarcinoma patient samples correlates with worse prognosis." (PMID 32784379, 2020). "Functional experiments from the same study show that MPC1 knockdown increases the volume of lung adenocarcinoma tumorspheres and stem cell marker expression." (PMID 32784379, 2020). "However, the clinical relevance and potential molecular mechanisms of MPC1 in lung adenocarcinoma (LAC) progression remain to be illustrated." (PMID 30770798, 2019). "The expression of MPC1 was significantly upregulated in the cholesterogenic group in KIRC, LGG, lung adenocarcinoma (LUAD) and LUSC, and the expression of MPC2 was significantly upregulated in the cholesterogenic group in PAAD, sarcoma (SARC) and CESC, similar to our findings in HCC." (PMID 32479426, 2020). "In addition, MPC1 expression was found to be substantially altered in five cancer types: breast-invasive carcinoma (BRCA), kidney renal clear cell carcinoma (KIRC), lung adenocarcinoma (LUAD), pancreatic adenocarcinoma (PAAD), and prostate adenocarcinoma (PRAD)." (PMID 34059057, 2021).
non-alcoholic fatty liver disease (5 papers, 2025). "The expression of mitochondrial pyruvate carrier 1 (MPC1) is positively correlated with hepatic lipid deposition in patients with nonalcoholic fatty liver disease, and lipid accumulation is reduced in the livers of MPC1+/− mice fed a high-fat diet." (PMID 40584617, 2025). "Non-histone lactylation, in non-alcoholic fatty liver disease (NAFLD), mitochondrial pyruvate carrier 1 (MPC1) regulates fatty acid synthase (FASN) lactylation, which in turn affects lipid metabolism and inflammation in hepatocytes." (PMID 39876839, 2025).
pancreatic cancer (5 papers, 2018 to 2024). "In pancreatic cancer, MPC1 was also reported to be transcriptionally suppressed by Lysine demethylase 5 A (KDM5A)-mediated demethylation H3K4." (PMID 38615083, 2024). "In the present study, we showed that suppression of MPC1 expression leads to EMT in pancreatic cancer and CRC cell lines as well as contributes to the acquisition of radioresistance." (PMID 30801869, 2019). "The present study has shown that reduced MPC1 expression is involved in EMT in pancreatic cancer and CRC cell lines." (PMID 30801869, 2019).
hepatocellular carcinoma (4 papers, 2020 to 2025). A malignant tumor that arises from hepatocytes. "We engineered HepG2 cells, which were originally isolated from a hepatocellular carcinoma, to express epitope-tagged MPC1 and MPC2 in a doxycycline-inducible manner." (PMID 41400249, 2025). "In hepatocellular carcinoma cells, PGC1α forms a complex with NRF1 and binds to the MPC1 promoter, ultimately increasing ROS formation and inducing apoptosis of HCC cells." (PMID 36902385, 2023).
ischemia (4 papers, 2019 to 2024). A hypoperfusion of the BLOOD through an organ or tissue caused by a PATHOLOGIC CONSTRICTION or obstruction of its BLOOD VESSELS, or an absence of BLOOD CIRCULATION. "In contrast, MPC1 level was significantly higher in ischemia-vulnerable CA1 then in CA2-4,DG in control conditions." (PMID 34445210, 2021).
ovarian carcinoma (4 papers, 2017 to 2024). A malignant neoplasm originating from the surface ovarian epithelium. "In our study, we demonstrate that MARCH5 functions as a key regulator of aerobic glycolysis by ubiquitinating MPC1 to promote ovarian cancer progression." (PMID 38615083, 2024). "Meanwhile, the UK5099 treated ovarian cancer cells expressed significantly higher levels of stamness markers, which all are similar to the MPC1 knockout cells." (PMID 28624784, 2017). "• Sevoflurane upregulated but propofol downregulated the GLUT1, MPC1, and GLUD1 expressions of ovarian cancer cells." (PMID 36207479, 2023). "The current study demonstrated that sevoflurane upregulated GLUT1, MPC1, and GLUD1 expressions of ovarian cancer cells, while propofol downregulated the expressions of these molecules." (PMID 36207479, 2023). "Therefore, MARCH5/MPC1 signaling may serve as a potential therapeutic target to normalize deranged glucose metabolism to suppress ovarian cancer progression." (PMID 38615083, 2024).
adenoma (3 papers, 2021 to 2023). A neoplasm arising from the epithelium. "The authors also showed in two different CRC mouse models that loss of Mpc1 led to upregulated glycolysis, increased expression of ISC markers, and increased frequency of adenoma formation with the generation of higher-grade tumors in response to a tumorigenic stimulus." (PMID 37190033, 2023). "In the AOM-DSS model, the deletion of Mpc1 in intestinal stem cells (Mpc1Lrig1 KO) increased the frequency of adenoma formation and the grade of tumor compared to that seen for Mpc1 WT animals, linking MPC loss with a greater susceptibility to tumor initiation after oncogenic stimulation." (PMID 33804985, 2021).
head and neck cancer (3 papers, 2018 to 2024). A primary or metastatic malignant neoplasm affecting the head and neck. "In head and neck cancer, MPC1 regulates ferroptosis in vivo and in vitro (You, Lee & Roh, 2021); meanwhile, recent studies have confirmed the significant role of ferroptosis in CRC; so, it may be promising to further study whether MPC1 can modulate ferroptosis in CRC." (PMID 34035992, 2021).
liver cancer (3 papers, 2018 to 2023). An epithelial or non-epithelial malignant neoplasm that arises from the liver. "The results implied that MPC1 is differentially expressed in various cancers; for example, MPC1 is expressed at lower levels in bladder, colorectal, oesophageal, gastric, kidney, and liver cancers than in adjacent normal tissues." (PMID 34059057, 2021).
bladder cancer (2 papers, 2015 to 2022). "The structural resemblance of 3-BrPA to pyruvate and lactate impelled us to examine the contribution of MCT1, MCT4 and SMCT1 plasma-membrane monocarboxylate transporters, as well as MPC1 and MPC2 mitochondrial pyruvate carrier components, to bladder cancer cell responsiveness to 3-BrPA." (PMID 26198749, 2015).
Breast Invasive Carcinoma (2 papers, 2018 to 2021). "In particular, we analyzed the MPC2/MPC1 expression ratio in normal and cancer tissues from the Breast Invasive Carcinoma (BRCA) dataset publicly available at The Cancer Genome Atlas project." (PMID 29472561, 2018).
cyst (2 papers, 2023 to 2025). A sac-like closed membranous structure that may be empty or contain fluid or amorphous material. "Thus, similar to the over-expression of Mpc1, manipulations that increase autonomous pyruvate consumption in cyst cells result in decreased germ cell survival." (PMID 40777312, 2025). "We also tested the impact of MPC1 deletion on cyst development in vivo." (PMID 36920199, 2023). "To test whether mitochondrial consumption of pyruvate in cyst cells would result in reduced lactate production and germ cell support, we increased mitochondrial import of pyruvate in cyst cells by over-expressing the Mitochondrial pyruvate carrier, Mpc1." (PMID 40777312, 2025).
diabetes (2 papers, 2022 to 2023). "In the gastrocnemius muscle, several genes involved in the Wnt signaling pathway were downregulated by diabetes, including Wnt2, Mpc1, Npnt, and Lrp6, whereas Fzd4 was higher in muscle from D mice." (PMID 38025035, 2023). "MPC1 is expressed in many organs, and we here present the first individual with the additional features of splenomegaly, bone fractures after minor trauma and insulin-dependent, anti-body negative diabetes mellitus." (PMID 36079864, 2022).
esophageal cancer (2 papers, 2018 to 2023). A primary or metastatic malignant neoplasm involving the esophagus. "qRT-PCR detection demonstrated increased expression of MPC1, COX6C, CYB5R3, CASP7, and CYCS in esophageal cancer patients." (PMID 38196829, 2023). "In addition, we found by qRT-PCR that the levels of MPC1, COX6C, CYB5R3, CASP7, and CYCS in tumor tissues of esophageal cancer patients were significantly higher than adjacent non-tumor tissues, suggesting that these genes may have some value in clinical diagnosis and prognosis." (PMID 38196829, 2023).
gastric cancer (2 papers, 2018 to 2021). A primary or metastatic malignant neoplasm involving the stomach. "In gastric cancer, the overexpression of MPC1 decreases the stem cell-like properties and sphere formation capability of tumour cells, and stemness markers such as NANOG, OCT4, SOX2, and β-actin are significantly decreased." (PMID 34059057, 2021). "In gastric cancer cell lines, the overexpression of MPC1 may attenuate proliferation, migration, and invasion." (PMID 34059057, 2021).
glioma (2 papers, 2022 to 2023). A benign or malignant brain and spinal cord tumor that arises from glial cells (astrocytes, oligodendrocytes, ependymal cells). "Lower levels of MPC1 (whether by deletion of its genomic locus or lower expression) are associated with poorer prognosis in gliomas and stronger Warburg effect." (PMID 36344581, 2022). "Interestingly, high MPC1 expression is strongly associated with a better prognosis in IDH-mutant and 1p/19q codel gliomas, but not GBM." (PMID 37108511, 2023).
heart failure (2 papers, 2019 to 2025). Inability of the heart to pump blood at an adequate rate to meet tissue metabolic requirements. "Studies have shown that MPC1 deficiency leads to cardiomyocyte hypertrophy and heart failure, whereas MPC1 overexpression attenuates the hypertrophic response of cardiomyocytes." (PMID 40357436, 2025). "Future work to elucidate mechanisms of altered expression and function for MPC1, MPC2, and PDK isoforms and their adaptations in heart failure progression will be valuable in the setting of mitochondrial energy regulation and the development of clinically viable novel drugs for these targets." (PMID 30881593, 2019).
Infertility (2 papers, 2015 to 2016). "Furthermore, it was suggested that MPC1 was a strong absorber and activator of uterine natural killer cells, which were associated with abortion and infertility." (PMID 26568760, 2015). "With these five MPC1−/− mice, mating experiments between MPC1−/− and MPC1−/− mice, and between MPC1−/− and WT mice were conducted for four months, but no single pregnancy was observed, highlighting the infertility of the homozygous MPC1 gene in KO mice." (PMID 27835892, 2016).
lactic acidosis (2 papers, 2016 to 2023). Metabolic acidosis characterized by the accumulation of lactate in the body. "In humans, mutations in MPC1 have been identified and associated with defects in mitochondrial pyruvate metabolism, lactic acidosis, hyperpyruvatemia, severe illness and failure to thrive." (PMID 27852261, 2016). "An increase in mt-i-tRFGlu(UUC) downregulates the expression of the nuclear gene mitochondrial pyruvate carrier 1 (MPC1), promoting the increase in extracellular lactate levels and leading to lactic acidosis, which is one of the well-known phenotypes of MELAS." (PMID 37298366, 2023).
Obesity (2 papers, 2023 to 2024). Accumulation of substantial excess body fat. "MPC1 abundance was found decreased in several kind of samples of individuals with obesity, including SKM or sperm, suggesting that a decrease in MPC1 may promote dysfunctional mitochondria metabolism in obesity." (PMID 38703299, 2024).
prostate tumor (2 papers, 2016 to 2021). "All these data support the conclusion that MPC1 plays an essential role in COUP-TFII induction of prostate tumor growth." (PMID 26895100, 2016). "The expression of COUP-TFII is negatively correlated with MPC1 in prostate tumor specimens." (PMID 34948229, 2021).
squamous cell carcinoma (2 papers, 2017 to 2018). A carcinoma arising from squamous epithelial cells. "Some studies report that a lower level of mitochondrial pyruvate carrier-1 (MPC-1) protein expression is related to poor survival rate in diverse types of tumors including lung, colon, kidney clear cell, prostate and esophagus squamous cell carcinomas." (PMID 30423827, 2018). "In contrast to esophageal squamous epithelium cells, decreased MPC protein expression was observed in a series of 157 human squamous cell carcinomas, and low/negative MPC1 expression predicted an unfavorable clinical outcome." (PMID 27911865, 2017).
bile duct cancer (1 paper, 2023). "Conversely, overexpression of PDHA1 and MPC1, along with PG-α, can counteract the Warburg effect and stimulate the proliferation of bile duct cancer cells." (PMID 38114959, 2023).
biliary tract cancer (1 paper, 2020). "Indeed, MPC1 expression was downregulated in human biliary tract cancer cells undergoing TGF-β (transforming growth factor beta)-induced EMT, and the knockdown of MPC1 expression led to induction of EMT in these cancer cells." (PMID 32708919, 2020).